RPL23 (ribosomal protein L23)
Diseases named in the same sentence as RPL23 in open-access papers:
RPL23 is named in the same sentence as 40 diseases in open-access papers, as found by Europe PMC text mining. Sharing a sentence is not in itself a finding about the gene and the disease. The quoted sentences say what the papers report.
gastric cancer (9 papers, 2011 to 2021). A primary or metastatic malignant neoplasm involving the stomach. "RPL23 was found to negatively regulate apoptosis via the RPL23/Miz-1/c-Myc circuit in a higher-risk myelodysplastic syndrome patient cell line, and it could promote multidrug resistance in gastric cancer cells by inhibiting drug-induced apoptosis." (PMID 34439131, 2021). "Interestingly, RPL23 reportedly causes growth inhibition and has anti-tumor effects in gastric cancer, SKM-1 and K562 cells, when it is suppressed." (PMID 30857280, 2019). "In gastric cancer cell lines, uS15 (rpS13), uL14 (rpL23) and eL6 (rpL6) are able to suppress drug-induced apoptosis and promote drug resistance, whereas eS1 (rpS3a) synergizes with drugs to induce apoptosis." (PMID 28085118, 2017). "For example, RPS3 is involved in the onset of cancer, RPS13 and RPL23 promote the multidrug resistance of gastric cancer cells, and RPL19 is involved in the prognosis of prostate cancer and CRC." (PMID 22272377, 2012). "Among these, RPL23 (rplW) has been identified as upregulated proteins in multidrug-resistant gastric cancer cell line and it could promote multi-resistant phenotype of gastric cancer cells." (PMID 31266490, 2019). "Human ribosomal protein L23 (RPL23), a classical RBP, has been reported to be involved in a variety of human cancers including lung cancer, myelodysplastic syndromes, gastric cancer, and colorectal cancer." (PMID 34926291, 2021). "Many RPs are found affected in gastric cancer (GC) including RPS13, RPL23, RPS27, RPL6, RPL13 and RPL15." (PMID 34873618, 2021).
hepatocellular carcinoma (4 papers, 2021 to 2025). A malignant tumor that arises from hepatocytes. "In hepatocellular carcinoma cells, RPL23 was shown to be associated with the matrix metalloproteinase MMP-9, where it helps to stimulate cell invasion." (PMID 40940922, 2025). "RPL23, a ribosomal protein responsible for translating mRNA into proteins, has been implicated in cancer progression across various cancer types, including lung cancer, colorectal cancer, and hepatocellular carcinoma." (PMID 38461424, 2024). "Consistent with this view, the level of RPL23 transcripts in tumour biopsies from patients with hepatocellular carcinoma was considerably higher than that of adjacent liver tissues." (PMID 40940922, 2025). "Moreover, the level of RPL23 protein in hepatocellular carcinoma tissues positively correlated with tumour invasion, tumour vascularization, lung metastasis and poor survival." (PMID 40940922, 2025).
lung carcinoma (4 papers, 2017 to 2024). "Overexpressed RPL23 has been reported to suppress tumor growth in lung cancer, but it is an unfavorable prognostic biomarker in ovarian cancer." (PMID 36341526, 2023).
ovarian carcinoma (4 papers, 2021 to 2024). A malignant neoplasm originating from the surface ovarian epithelium. "We postulate that RPL23 plays a positive role in ovarian cancer progression, potentially linked to immune function and oxidative phosphorylation." (PMID 38461424, 2024). "The risk scoring model constructed based on 12 genes including RPL23 provided important evidence for further understanding the mechanism of the occurrence and development of ovarian cancer." (PMID 39478854, 2024). "Additionally, we constructed a prognostic model relevant to ovarian cancer, emphasizing the potential significance of the high-risk gene RPL23 and the Oxidative Phosphorylation pathway as crucial targets for ovarian cancer treatment and drug resistance." (PMID 38461424, 2024). "PKM2, MRPS12, NDUFC2, HPDL, MRPL14, COA6 and RNF144B were significantly upregulated in ovarian cancer tissues than in normal tissues (P < 0.05), while RPL23, FGFR1OP2, CAPN10, ALDH1L1 and ACSM1 were significantly down-regulated (P < 0.05)." (PMID 39478854, 2024). "Kang and colleagues have also identified RPL23’s role in promoting ovarian cancer cell progression, suggesting that its high expression may facilitate ovarian cancer recurrence, aligning with our research findings." (PMID 38461424, 2024). "Therefore, we suggest USP19 and RPL23 as candidate biomarkers for predicting the survival of patients with ovarian cancer." (PMID 34439131, 2021). "In the present study, RPL23, FGFR1OP2, CAPN10, ALDH1L1 and ACSM1 were significantly downregulated in ovarian cancer, while the up-regulation of RPL23, FGFR1OP2, CAPN10 and ALDH1L1 was associated with poor prognosis in patients with ovarian cancer." (PMID 39478854, 2024). "Biomarkers such as RPL23, MRPS12, and ALDH1L1 have been used to predict the prognosis of ovarian cancer, but most studies focus on the prognostic role of a single biomarker." (PMID 39478854, 2024).
viral infection (4 papers, 2011 to 2025). "After viral infection, the midgut and the salivary gland from RpL23 and RpL27 dsRNA-treated mosquitoes were dissected for virus detection by qPCR." (PMID 34061577, 2021).
breast carcinoma (3 papers, 2018 to 2021). "CNVs of RPL19 and RPL23 in breast cancer likely occur due to their co-amplification with ERBB2 on 17q12." (PMID 29530001, 2018). "Furthermore, the other two hub genes, RPL37 and RPL23, were identified in the expression profiling of the cDNA-based microarray in response to 5-FU in a breast cancer cell though without subsequent validation." (PMID 31662984, 2019).
COVID-19 (3 papers, 2022 to 2023). A disease caused by infection with severe acute respiratory syndrome coronavirus 2. "There was a positive correlation between COVID-19-related protein RPL23 and LYN." (PMID 35720320, 2022).
melanoma (3 papers, 2012 to 2025). A malignant, usually aggressive tumor composed of atypical, neoplastic melanocytes. "Furthermore, we found four RPL/RPS members of the melanoma CTC signature (RPL23, RPL35A, RPL6, and RPS18) of 21 RPL/RPS genes to be keenly involved in metastatic progression." (PMID 39831781, 2025). "The custom-designed 10× Xenium gene panel contained 30 human genes, including pathologically established BCR and S100A1 melanoma markers and RPL23 and RPL35A as the most representative members of the melanoma CTC signature." (PMID 39831781, 2025). "In 2017, Patel used the CRISPR system, together with a machine-learning computational model, to identify genes essential for tumor progression in melanoma cell lines, such as collagen type XVII alpha 1 (COL17A1), twinfilin-1 (TWF1), microRNA 101-2 (Hsa-Mir-101-2) and ribosomal protein L23 (RPL23)." (PMID 39696697, 2024).
myelodysplastic syndrome (3 papers, 2017 to 2021). A clonal hematopoietic disorder characterized by dysplasia and ineffective hematopoiesis in one or more of the hematopoietic cell lines. "Ribosomal protein (RP) L23 is a negative regulator of cellular apoptosis, and RPL23 overexpression is associated with abnormal apoptotic resistance in CD34+ cells derived from patients with higher-risk myelodysplastic syndrome (MDS)." (PMID 28539603, 2017). "For example, in higher-risk myelodysplastic syndrome (MDS) patients, studies showed that overexpression of RPL23 was associated with the abnormal apoptotic resistance in CD34+ cells." (PMID 34926291, 2021).
acute myeloid leukaemia (2 papers, 2019). "Furthermore, compared to patients with normal levels of RPL23, patients with high levels of RPL23 were significantly more likely to develop acute myeloid leukemia and a correspondingly reduced survival rate." (PMID 31338556, 2019).
Shwachman-Diamond syndrome (2 papers, 2018 to 2023). "The dynamics of eIF6 interaction with the uL14 (RPL23) interface of 60S and its perturbation by somatic mutations acquired in Shwachman–Diamond Syndrome (SDS) is yet to be clearly understood." (PMID 36651285, 2023). "Gene expression profiles of bone marrow mononuclear cells from patients with Shwachman-Diamond syndrome revealed significant downregulation of RP genes, including RPS9, RPS20, RPL6, RPL15, RPL23, and RPL29, or upregulation of RPS27." (PMID 29954325, 2018).
ZIKV infection (2 papers, 2021 to 2025). "In the present study, 73% of ribosomal protein genes in A. aegypti were upregulated after ZIKV infection, and silencing of RpL23 and RpL27 significantly attenuated ZIKV infection." (PMID 34061577, 2021). "Ribosomal proteins RpL23 and RpL27 are critical for ZIKV infection, and they can be directly regulated by the JH-receptor complex." (PMID 34061577, 2021). "Silencing of RpL23 and RpL27, two ribosomal large subunit genes, increased mosquito resistance to ZIKV infection." (PMID 34061577, 2021). "In addition, RNA interference (RNAi) silencing of RpL23 and RpL27, two JH-regulated ribosomal large subunit genes, suppressed ZIKV infection in A. aegypti." (PMID 34061577, 2021). "Moreover, the upregulated expression of RpL23 and RpL27 could facilitate the translation of viral proteins and promotes ZIKV infection in Aedes aegypti." (PMID 40806613, 2025).
arterial diseases (1 paper, 2021). "RPL23 is involved in apoptosis, but putative roles in arterial diseases in diabetes remain to be investigated." (PMID 34496837, 2021).
liver cancer (1 paper, 2021). An epithelial or non-epithelial malignant neoplasm that arises from the liver. "In addition, the mRNA and protein level of RPL23 was dramatically increased in a panel of liver cancer cells compared to primary hepatocytes (PHH)." (PMID 34926291, 2021).
lymphoma (1 paper, 2023). A malignant (clonal) proliferation of B- lymphocytes or T- lymphocytes which involves the lymph nodes, bone marrow and/or extranodal sites.
Sepsis (1 paper, 2025). Sepsis is defined as life-threatening organ dysfunction caused by a dysregulated host response to infection. "Significant expression of the ribophagy-specific receptor NUFIP1 and autophagy-associated protein LC-3B was observed in CD4+ T lymphocytes after sepsis, with a corresponding decrease in the expression of ribosomal self-proteins ribosomal protein L7 (RPL7), RPL23, and RPL26." (PMID 40995563, 2025).
cancer (18 papers, 2012 to 2025). A tumor composed of atypical neoplastic, often pleomorphic cells that invade other tissues. "There are approximately 80 RPs in eukaryotic ribosomes, and RPL23 has been reported to be associated with multidrug resistance and cancer progression." (PMID 34439131, 2021). "Moreover, RPL23 overexpression was clearly associated with advanced tumor grade (p<0.0001) and late cancer stage (p<0.0001)." (PMID 34926291, 2021). "Moreover, studies using artificial intelligence have identified genes like Ubiquitin carboxyl-terminal hydrolase 19 (USP19) and RPL23 as crucial for predicting cancer recurrence." (PMID 39891297, 2025). "Given that RPL23 is an RNA-binding protein which can regulate human cancer progress by influencing RNA stability, We then performed experiments to elucidate whether the decreased MMP9 mRNA levels were due to a change in RNA synthesis or decay." (PMID 34926291, 2021). "Therefore, 6 of the genes (ENC1, ACAT1, MSTC1, MADCAM1, RPL23 and SNRPB2) were found to be associated with cancer, genetic disorder or reproductive system disease within the same network." (PMID 22280244, 2012). "Additionally, some recent studies revealed that RPL23 might play an important role in cancer metastasis due to its regulatory function on RNA metabolism." (PMID 34926291, 2021). "Cancer recurrence occurred more frequently in the patients with lower USP19 mRNA levels and those with higher RPL23 mRNA levels." (PMID 34439131, 2021). "In the current study, besides the role of RPL23 on invasive ability in HCC cells, we found that knockdown of RPL23 resulted in the decrease of F-actin filaments, a cytoskeleton constituent that plays critical role in cancer metastasis." (PMID 34926291, 2021). "Previous evidences demonstrate that c-Myc and its regulated ribosomal biogenesis by ribosomal RNA synthesis and processing are critically involved in cancer progression and ribosomal protein L5 (RPL5), RPL11, and RPL23 regulates apoptosis in response to ribosomal stress." (PMID 31574980, 2019). "Cancer cells show the characteristics of immortalization and absence of senescence; thus, these two cell lines, including the RPL23-knockdown and blank/negative control groups, barely showed any senescent signals." (PMID 28539603, 2017).
tumor (16 papers, 2016 to 2025). "RPL23 can promote tumour cell replication by negatively regulating Myc-interacting zinc finger protein 1 (Miz-1) dependent transcription of the cell cycle inhibitors P15lnk4b and P21cip1." (PMID 40940922, 2025). "In this study, RPL23 was identified as a tumor-promoting oncogene that plays an important role in HCC." (PMID 34926291, 2021). "Consistent with in vitro observation, knockdown of RPL23 significantly decreased both the tumor growth rate and tumor size in liver." (PMID 34926291, 2021). "Moreover, the expression level of RPL23 was positively corelated to tumor vascular invasion (p=0.0070), lung metastasis (p=0.0469) and TNM stage (p=0.0346) in HCC." (PMID 34926291, 2021). "Here, we identified RNA binding protein L23 (RPL23) as a tumor metastasis driver in HCC." (PMID 34926291, 2021). "coli), RPLP0 (tumor progression, invasion, metastasis), RPS5, RPL9, RPS14, RPS2, RPL3, and RPL23." (PMID 34445327, 2021). "Taken together, those data indicated that elevated RPL23 may involve in HCC metastasis and tumor progression." (PMID 34926291, 2021).
infection (8 papers, 2011 to 2025). The state of being infected such as from the introduction of a foreign agent such as serum, vaccine, antigenic substance or organism. "Upon infection, the expression of mRpS11, RpL23, and RpL27 was significantly upregulated in midgut 1 dpi or fat body 7 dpi." (PMID 34061577, 2021). "Interesting to note is that the average viral titer of IAPV in the fat body was around 1400 times the normalized level of the reference genes rpl23 and ubi, whereas for CrPV it was only 16 times, even with an infection dose of only 500 particles of IAPV and 106 of CrPV." (PMID 27999371, 2016). "During the early stages of infection, Zika virus (ZIKV) regulates the expression of some ribosomal protein genes (RpL23 and RpL27) through the JH-Met-Tai signalling pathway." (PMID 40806613, 2025). "We next investigated the interaction between RPLs (RPL11 and RPL23) and MDM2 during different time points post-infection (8 hpi and 24 hpi)." (PMID 29259342, 2017). "Due to the vulnerable cellular characteristics of RPL23-KD SKM-1 cells, we used a multiplicity of infection (MOI) of 10 for LV-RPL23-RNAi transfection without fluorescence-activated cell sorting (FACS)." (PMID 28539603, 2017).
RPL23 also shares sentences with these, for which no sentence is quoted: Alzheimer disease (2 papers); colorectal cancer (2); nasopharyngeal carcinoma (2); albinism (1); autism (1); autoimmune disease (1); B cell lymphoma (1); bacterial infections (1); cervical cancer (1); diabetes (1); genetic disorder (1); lung adenocarcinoma (1); lymph node metastasis (1); osteosarcoma (1); parathyroid adenoma (1); prostate carcinoma (1); reproductive system disease (1); schizophrenia (1); Serous Ovarian Carcinoma (1); squamous cell carcinoma (1); triple-negative breast carcinoma (1).